FXN (frataxin)
Description:
[Frataxin mature form]: Functions as an activator of persulfide transfer to the scaffoding protein ISCU as component of the core iron-sulfur cluster (ISC) assembly complex and participates to the [2Fe-2S] cluster assembly. Accelerates sulfur transfer from NFS1 persulfide intermediate to ISCU and to small thiols such as L-cysteine and glutathione leading to persulfuration of these thiols and ultimately sulfide release. Binds ferrous ion and is released from FXN upon the addition of both L-cysteine and reduced FDX2 during [2Fe-2S] cluster assembly. The core iron-sulfur cluster (ISC) assembly complex is involved in the de novo synthesis of a [2Fe-2S] cluster, the first step of the mitochondrial iron-sulfur protein biogenesis. This process is initiated by the cysteine desulfurase complex (NFS1:LYRM4:NDUFAB1) that produces persulfide which is delivered on the scaffold protein ISCU in a FXN-dependent manner. Then this complex is stabilized by FDX2 which provides reducing equivalents to accomplish the [2Fe-2S] cluster assembly. Finally, the [2Fe-2S] cluster is transferred from ISCU to chaperone proteins, including HSCB, HSPA9 and GLRX5 (By similarity). May play a role in the protection against iron-catalyzed oxidative stress through its ability to catalyze the oxidation of Fe(2+) to Fe(3+); the oligomeric form but not the monomeric form has in vitro ferroxidase activity. May be able to store large amounts of iron in the form of a ferrihydrite mineral by oligomerization; however, the physiological relevance is unsure as reports are conflicting and the function has only been shown using heterologous overexpression systems. May function as an iron chaperone protein that protects the aconitase [4Fe-4S]2+ cluster from disassembly and promotes enzyme reactivation. May play a role as a high affinity iron binding partner for FECH that is capable of both delivering iron to ferrochelatase and mediating the terminal step in mitochondrial heme biosynthesis. [Extramitochondrial frataxin]: Modulates the RNA-binding activity of ACO1. May be involved in the cytoplasmic iron-sulfur protein biogenesis. May contribute to oxidative stress resistance and overall cell survival.
Synonyms: FRDA; X25; FA; FARR; CyaY
Tractability: Small molecule: a structure with a bound ligand is known. PROTAC: ubiquitination databases record sites on it; its protein half-life has been measured.
Target class: Enzyme; Oxidoreductase
Gene: Protein-coding gene on chromosome 9 (69,035,750 to 69,079,076, forward strand). Ensembl gene ENSG00000165060.
Subcellular location: Mitochondrion (Frataxin mature form); Cytoplasm, cytosol (Extramitochondrial frataxin)
Subcellular location (Human Protein Atlas): Mitochondria; Cytosol
Pathways (Reactome):
Metabolism: Complex III assembly; Maturation of TCA enzymes and regulation of TCA cycle; Mitochondrial iron-sulfur cluster biogenesis
Protein localization: Mitochondrial protein import
Gene Ontology:
Molecular function: 2 iron, 2 sulfur cluster binding; enzyme activator activity; ferric iron binding; ferrous iron binding; ferroxidase activity; iron chaperone activity; protein binding
Biological process: [2Fe-2S] cluster assembly; [4Fe-4S] cluster assembly; cellular response to hydrogen peroxide; heme biosynthetic process; intracellular iron ion homeostasis; iron-sulfur cluster assembly; negative regulation of apoptotic process; negative regulation of release of cytochrome c from mitochondria; positive regulation of lyase activity; protein autoprocessing; protein maturation; response to iron ion; mitochondrial respiratory chain complex III assembly; inorganic ion homeostasis; intracellular monoatomic cation homeostasis
Cellular component: cytosol; mitochondrial [2Fe-2S] assembly complex; mitochondrion; iron-sulfur cluster assembly complex; mitochondrial matrix
Genetic constraint (gnomAD): Loss-of-function variants: 8 observed, 17.84 expected, observed/expected ratio (o/e) 0.45, 90% interval 0.26 to 0.81. The upper end of that interval is the gene's LOEUF score, 0.81, which puts it in group 3 of 6, group 1 being the genes least tolerant of losing a copy. Missense variants: 236 observed, 218.15 expected, observed/expected ratio (o/e) 1.08, 90% interval 0.97 to 1.21. Synonymous variants: 107 observed, 96.15 expected, observed/expected ratio (o/e) 1.11, 90% interval 0.95 to 1.31.
Gene-disease validity (ClinGen):
ClinGen rates the evidence that FXN causes each of these diseases.
Friedreich ataxia (autosomal recessive): Definitive. An inherited condition that affects the nervous system and causes movement problems.
Homologues: Orthologues: chimpanzee FXN (99% identical), macaque FXN (92% identical), guinea pig FXN (79% identical), pig FXN (76% identical), mouse Fxn (73% identical), rabbit FXN (72% identical), dog FXN (71% identical), rat Fxn (55% identical), tropical clawed frog fxn (54% identical), zebrafish fxn (41% identical), Drosophila melanogaster fh (36% identical), Caenorhabditis elegans frh-1 (27% identical).
Diseases named in the same sentence as FXN in open-access papers:
FXN is named in the same sentence as 153 diseases in open-access papers, as found by Europe PMC text mining. Sharing a sentence is not in itself a finding about the gene and the disease. The quoted sentences say what the papers report.
Friedreich ataxia (456 papers, 2006 to 2026). "Initial genetic analysis revealed that both siblings also harbor FXN GAA repeat expansions consistent with pathogenic Friedreich’s ataxia (FRDA)." (PMID 41596228, 2026). "Friedreich's ataxia (FA) is a progressive autosomal recessive neurodegenerative disorder caused by frataxin (FXN) deficiency, resulting in mitochondrial dysfunction, oxidative stress, defective autophagy, and progressive motor impairment." (PMID 42240896, 2026). "Frataxin is a conserved mitochondrial protein essential for cellular iron-sulfur (Fe-S) cluster biogenesis and oxidative balance, with its deficiency causing Friedreich's ataxia in humans." (PMID 42042415, 2026). "Friedreich's ataxia (FRDA) is an autosomal recessive neurodegenerative disease caused by a GAA repeat expansion in the frataxin (FXN) gene, leading to reduced frataxin, a protein essential for mitochondrial function." (PMID 42134333, 2026). "We show that lowering levels of wild-type FDX2 through loss of one gene copy can ameliorate the growth of frataxin mutant C. elegans or the ataxia phenotype of a mouse model of Friedreich’s ataxia under normoxic conditions." (PMID 41372402, 2026). "Friedreich Ataxia (caused by mutations in the FXN gene) presents a broader dysregulation of mitochondrial iron across various tissues, including the brain, heart, and skeletal muscle." (PMID 40597358, 2025). "Friedreich ataxia is caused by mutations in the frataxin gene, leading to neurodegeneration and premature death from cardiac dysfunction." (PMID 40744695, 2025). "Among patients suffering from ataxia (n = 13), 5 patients had Friedreich ataxia associated with homozygous expansion in the FXN gene, while 2 patients had a single nucleotide pathogenic variant in this gene and a compound heterozygous expansion." (PMID 40883749, 2025). "In humans, FXN mutations link to Friedreich’s ataxia as the most common form of autosomal recessive ataxia displaying with severe neurodegenerative pathology." (PMID 40904733, 2025). "HDACi have also been studied for Friedreich’s ataxia, a neurodegenerative disorder caused by a significant reduction in frataxin levels, due to a large GAA triplet repeat expansion within the first intron of the frataxin gene (FXN)." (PMID 41155586, 2025). "Deficiency in frataxin is associated with Friedreich's ataxia, a progressive neurodegenerative disorder." (PMID 41147201, 2025). "Background/Objectives: Friedreich’s ataxia (FA) is a rare neurodegenerative disorder caused by GAA repeat expansions in the FXN gene." (PMID 41301739, 2025). "Friedreich's ataxia, a recessive disorder caused by a mutation in the frataxin (FXN) gene, has few mouse models that demonstrate a progressive behavioral decline paralleling that of patients." (PMID 40017373, 2025). "Friedreich’s ataxia is caused by a deficiency in the protein frataxin, which plays a key role in mitochondrial iron metabolism, so its deficiency leads to mitochondrial dysfunction, oxidative stress, and other issues." (PMID 40650152, 2025). "Treatment with antisense oligonucleotides (ASOs) covering intronic splicing regulator motifs resulted in increased FXN expression from the point mutation allele in Friedreich’s ataxia fibroblasts and from a miniFXN gene carrying the same mutation." (PMID 40704029, 2025). "Friedreich's ataxia (FRDA) is a recessive inherited ataxia caused by intronic GAA repeat expansions in FXN gene." (PMID 40994821, 2025). "Friedreich’s ataxia (FRDA) is an autosomal recessive neurodegenerative spinocerebellar ataxia caused by a homozygous GAA triplet repeat expansion in the frataxin (FXN) gene." (PMID 41176519, 2025). "Repeat expansions, such as those in HTT (CAG repeats in Huntington’s disease), ATXN1 and ATXN2 (CAG repeats in spinocerebellar ataxias), and FXN (GAA repeats in Friedreich’s ataxia), are well-established causes of neurodegenerative disorders." (PMID 40166539, 2025).
Friedreich ataxia (continued). "Frataxin is a component of the iron–sulfur (Fe-S) cluster assembly complex in mitochondria, and deficiency is associated with Friedreich ataxia (FA)." (PMID 40563426, 2025). "Friedreich's Ataxia (FRDA) is a neuromuscular degenerative disorder caused by trinucleotide expansions in the first intron of the frataxin (FXN) gene, resulting in insufficient levels of functional FNX protein." (PMID 38746130, 2024). "In a previous study using a frataxin knockdown mouse model, we observed several hallmark Friedreich’s ataxia symptoms." (PMID 38846537, 2024). "Friedreich’s ataxia, the most common dysfunction of FeS cluster biosynthesis, is caused by decreased function of FXN in mitochondria, resulting in neuronal degeneration." (PMID 39632806, 2024). "Data on FXN mutations were obtained from the Friedreich Ataxia Clinical Outcome Measures Study (FA‐COMS)." (PMID 38396238, 2024). "Friedreich’s Ataxia is a group of chronic, progressive, autosomal recessive neurodegenerative diseases caused by decreased frataxin expression due to the amplification of GAA triplet repeats within the first intron of the frataxin gene." (PMID 39396974, 2024). "Frataxin, central to Friedreich's ataxia pathology, exists in two primary forms: mitochondrial frataxin (frataxin-M) and an erythrocyte-specific variant (frataxin-E)." (PMID 38846537, 2024). "In Friedreich ataxia, a similar autosomal recessive disorder caused by repeat expansion in FXN, LTL shortening, has been reported in patient leukocytes." (PMID 38324175, 2024). "Subsequent DNA analysis aimed at assessing the number of trinucleotide repeats in the ATX1, ATX2, ATX3, ATX7, ATX8, and FXN genes, responsible for various spinocerebellar ataxia variants and Friedreich’s ataxia, revealed a normal number of repeats." (PMID 39596606, 2024). "Mutation of the gene encoding FXN, a subunit of core Fe-S assembly complex, causes Friedreich’s ataxia." (PMID 39151727, 2024). "Friedreich's ataxia (FA) is an autosomal recessive genetic disease caused mainly by GAA repeats in the FXN gene, with the shorter GAA1 allele more closely linked to disease progression." (PMID 38520521, 2024). "Friedreich ataxia (FRDA) is an autosomal recessive neurodegenerative disease caused by pathogenic variants in the FXN gene which encodes for the mitochondrial protein frataxin." (PMID 38814901, 2024). "Multiple PPARγ agonists, including PGZ, are capable of increasing the expression of FXN in the models of Friedreich Ataxia, a neurological disorder caused by FXN deficiency." (PMID 39334695, 2024). "Friedreich ataxia (FRDA) is a rare genetic disorder caused by mutations in the FXN gene, leading to progressive coordination loss and other symptoms." (PMID 38556905, 2024). "Friedreich ataxia (FRDA) is an autosomal recessive neurodegenerative disorder resulting from deficiency of the protein frataxin." (PMID 37691319, 2024). "Mutations in the frataxin (FXN) gene play a critical role in the development of Friedreich’s ataxia (FRDA), a neurodegenerative disorder characterized by progressive muscle weakness and impaired coordination." (PMID 38631900, 2024). "Friedreich’s ataxia is an autosomal recessive spinocerebellar ataxia resulting from mutations in the FXN gene, which encodes the protein frataxin." (PMID 38790635, 2024). "Friedreich ataxia (FA) is a rare, progressive, neuromuscular disease caused by a recessive mutation in the frataxin (FXN) gene that limits the production of frataxin protein." (PMID 38261944, 2024). "FXN deficiency in humans causes Friedreich ataxia (FRDA), an inherited degenerative syndrome characterized by central and peripheral neuropathy, accompanying cardiomyopathy, with a high incidence of diabetes." (PMID 39334695, 2024). "Genetic mutations in the human ISC genes impair this process and cause severe metabolic, neurological and hematological diseases, often with fatal outcomes, the most prevalent being Friedreich’s ataxia with mutations in the frataxin (FXN) gene." (PMID 38627381, 2024).
Friedreich ataxia (continued). "Friedreich's ataxia is a degenerative and progressive multisystem disorder caused by mutations in the highly conserved frataxin (FXN) gene that results in FXN protein deficiency and mitochondrial dysfunction." (PMID 38234818, 2023). "Humans with a deficiency of frataxin, the human homolog of Yfh1, suffer from Friedreich’s Ataxia, a neurodegenerative mitochondrial disease that involves iron dysregulation." (PMID 38113197, 2023). "Friedreich’s ataxia (FA) is a predominantly neurodegenerative disease caused by recessive mutations that produce a deficiency of frataxin (FXN)." (PMID 37251644, 2023). "Deficiency in human mature frataxin (hFXN-M) protein is responsible for the devastating neurodegenerative and cardiodegenerative disease of Friedreich’s ataxia (FRDA)." (PMID 37461697, 2023). "Friedreich ataxia (FRDA) is a progressive neurodegenerative disease caused by a GAA repeat in the intron 1 of the frataxin gene (FXN) leading to a lower expression of the frataxin protein." (PMID 37628705, 2023). "Friedreich ataxia (FRDA) is a rare genetic multisystem disorder caused by a pathological GAA trinucleotide repeat expansion in the FXN gene." (PMID 37726850, 2023). "Heart disease in Friedreich ataxia (FA), a genetic neurodegenerative disease caused by decreased levels of frataxin (FXN) protein, is the leading cause of mortality." (PMID 37691621, 2023). "Friedreich ataxia (FA) is a rare, recessive neuro-cardiodegenerative disease caused by deficiency of the mitochondrial protein frataxin." (PMID 38129330, 2023). "Friedreich ataxia results from a GAA repeat expansion in the FXN gene, which encodes the protein frataxin that is localized to mitochondria." (PMID 37374132, 2023). "Three cellular states were analyzed including healthy wild-type cells, iron-deficient wild-type cells, and a frataxin-deficient strain of cells characterizing the disease Friedreich’s Ataxia." (PMID 38113197, 2023). "FA (Friedreich’s ataxia) is a recessive, predominantly neurodegenerative disorder caused by mutations in the first intron of the Fxn (frataxin) gene." (PMID 37833867, 2023). "Friedreich’s ataxia (FRDA) is caused by a decrease in mitochondrial proteins frataxin (FXN), and one of the features is an iron overload on the mitochondria." (PMID 37373183, 2023). "This is particularly interesting for CANVAS, as Friedreich ataxia, another autosomal recessive neurodegenerative disease caused by A-rich repeat expansions, exhibits a marked reduction in mRNA and protein dosing of frataxin." (PMID 35563872, 2022). "Friedreich’s ataxia (FA) is a currently incurable genetic disease caused by the expansion of the trinucleotide GAA within intron 1 of the frataxin (FXN) gene." (PMID 35289725, 2022). "By knocking out Frataxin in mice, researchers generated a model that recapitulated most features of Friedreich’s ataxia (FRDA)-associated cardiomyopathy." (PMID 36359908, 2022). "Studies have shown that reduced levels of FXN are responsible for causing the neurodegenerative disease of Friedreich's ataxia." (PMID 36338346, 2022). "Dyclonine was proposed as a candidate therapeutic for Friedreich ataxia for its ability to increase frataxin levels and rescue downstream consequences of frataxin deficiency." (PMID 35221903, 2022). "Friedreich’s ataxia (FRDA) is a rare neurodegenerative disease caused by GAA triplet-repeat expansions in the FXN gene, which encodes the protein frataxin." (PMID 34652504, 2022). "Friedreich’s ataxia is an incurable disease caused by frataxin (FXN) protein deficiency, which is mostly induced by GAA repeat expansion in intron 1 of the FXN gene." (PMID 36511872, 2022). "Friedreich’s ataxia (FRDA) is an autosomal recessive neurodegenerative disorder caused by the deficient expression of mitochondrial mature frataxin protein." (PMID 35573317, 2022).